RNU6-755P (RNA, U6 small nuclear 755, pseudogene)
Gene: Small nuclear RNA gene on chromosome 1 (164,980,035 to 164,980,137, reverse strand). Ensembl gene ENSG00000201270.
Homologues: Orthologues: chimpanzee U6 (99% identical), macaque U6 (92% identical), dog U6 (71% identical), rabbit U6 (53% identical), guinea pig U6 (43% identical). Paralogues in human: RNU6-829P (84% identical), RNU6-1019P (81% identical), RNU6-1060P (81% identical), RNU6-166P (81% identical), RNU6-41P (81% identical), RNU6-44P (81% identical), RNU6-47P (81% identical), RNU6-517P (81% identical), RNU6-589P (81% identical), RNU6-619P (81% identical), RNU6-657P (81% identical), RNU6-847P (81% identical), and 1287 more.